PF4 (platelet factor 4)
Diseases named in the same sentence as PF4 in open-access papers (continued):
Sharing a sentence is not in itself a finding about the gene and the disease.
autoimmune disease (15 papers, 2015 to 2025). A disorder resulting from loss of function or tissue destruction of an organ or multiple organs, arising from humoral or cellular immune responses of the individual to their own tissue constituents. "Heparin-induced thrombocytopenia (HIT) is a type of autoimmune disease caused by platelet-activating antibodies that recognize the multimolecular complexes of platelet factor 4 (PF4) bound to heparin." (PMID 31139417, 2019). "In particular it may be due the production of autoantibodies against the Platelet Factor-4 (PF4) in individuals susceptible to autoimmune diseases." (PMID 34200989, 2021). "Anti-PF4 autoantibodies have also been detected in several autoimmune diseases (e.g., SLE, systemic sclerosis, and RA)." (PMID 37759488, 2023). "We hypothesized that sera from patients with autoimmune diseases contain autoantibodies to PF4 that activate integrins in the presence of wt PF4." (PMID 41226302, 2025). "Also, this PF4 mutant acted as an antagonist for PF4/anti-PF4-induced integrin activation and has potential as an antagonist for PF4-induced autoimmune diseases." (PMID 41226302, 2025). "We also showed that PF4/anti-PF4 potently activated vascular integrin αvβ3, which may play a critical role in autoimmune diseases." (PMID 37759488, 2023). "Transferring the mechanism of the anti-PF4 autoimmune process to other autoimmune disorders may explain an unresolved issue regarding the pathogenicity of certain autoantibodies." (PMID 28530237, 2017). "Since heparin-independent anti-PF4 has been detected in autoimmune diseases and the levels of anti-PF4 correlate with disease progression, activation of integrins by anti-PF4/PF4 complex may be involved in the pathogenesis of autoimmune diseases." (PMID 41226302, 2025). "The PF4 mutant defective in binding to site 2 is a potential antagonist of anti-PF4-induced VITT and autoimmune diseases." (PMID 41226302, 2025). "Since autoantibodies to PF4 are detected in vaccine-induced thrombocytopenic thrombosis (VIPP) and autoimmune diseases (e.g., SLE, and rheumatoid arthritis), we propose that this phenomenon is related to the pathogenesis of these diseases." (PMID 37759488, 2023). "We hypothesized that autoanti-PF4 antibody is present in sera of patients with autoimmune diseases (e.g., SLE and RA), and such autoanti-PF4 induces autoimmune diseases." (PMID 41226302, 2025). "Nonspecific autoantibodies even with epitope specificity, including the antibodies against the molecules of PF4 or PL alone, are unlikely to provoke autoimmune disease." (PMID 36143988, 2022). "Also, anti-PF4 may be involved in the pathogenesis of autoimmune diseases by activation of αvβ3 and other integrins in non-platelet cells (e.g., monocytes)." (PMID 41226302, 2025). "Overall, data is suggesting that PF4 autoantibodies and HITT can arise through mechanisms similar to other autoimmune disorders, without requiring sensitization by a specific neoantigen." (PMID 38140254, 2023).
breast carcinoma (15 papers, 2014 to 2025). "The set of selected genes was composed of a group of angiogenesis-related genes (VEGF, PDGF, ANG-1, and PF-4) and genes that have been previously associated with carcinogenic or metastatic processes in breast cancer (WASF3, LAPTM4B, TPM3, and TAC1)." (PMID 37176055, 2023). "In contrast, in patients with HER2+ breast cancer, the expression of PF4 increased only in tumor tissue." (PMID 37176055, 2023). "Genes related to angiogenesis processes, such as VEGF, PDGF, ANG-1, and PF-4, were differentially expressed in luminal A in breast cancer tissue and in platelets from patients with BC." (PMID 37176055, 2023). "PF4 has been found to downregulate the vascular endothelial growth factor VEGF in breast cancer (TA3) and ovarian cancer (SKOV-3 and ES-2) cell lines, and thus, inhibit tumor growth and induce apoptosis." (PMID 34440575, 2021). "Since there are no available measurements of the PF4 level directly from tumor tissue sample, we use the measured blood PF4 level in breast cancer patients as an estimation of tumor interstitial PF4 level." (PMID 31379588, 2019). "Circulating platelets in breast cancer sequester higher levels of PF4, VEGF, PDGF-BB, and TGF-β1, suggesting a possible target for early diagnosis." (PMID 25379550, 2014). "The binding of PF4 to breast cancer cells may be charge-related as cancer cells exhibit a high density of polyanions such as chondroitin sulfate, polyphosphates, or glycosaminoglycan (GAG)." (PMID 34440575, 2021). "We first analyzed breast cancer cohorts in “The Cancer Genome Atlas” (TCGA), Oncomine, and found that high PF4 levels correlated with increased survival of breast cancer patients; and that decreased PF4 levels are observed in stage III/IV compared with stage I/II in breast cancer progression." (PMID 27223426, 2017). "First, PF4 is produced in normal Ly6G+CD11b+ myeloid cells; Second, PF4 expression level is decreased in these myeloid cells from lungs of late stage tumor-bearing mice compared to that from normal or early stage tumor-bearing mice, consistent in both 4T1 mammary tumor model and B16 melanoma model." (PMID 27223426, 2017). "Here, we investigated the effect of HIT components including heparin, PF4, PF4/H complexes, and the combination of PF4/H complexes with RTO, KKO antibodies on the development of breast cancer cells." (PMID 34440575, 2021). "Our results indicate that HIT components, especially the PF4 or KKO in complexed with PF4/Heparin, modified the mechanical property of breast cancer cells and interfered with cell spreading and proliferation." (PMID 34440575, 2021). "In conclusion, we found that circulating platelets in breast cancer sequester higher levels of PF4, VEGF, PDGF-BB, and TGF-β1, and these proteins can be possible indicators for breast cancer in early diagnosis." (PMID 25379550, 2014). "Even though the binding mechanism of RTO and KKO antibodies to breast cancer cells remains unclear, the RTO is known to bind only to a single PF4 monomer while the KKO is intercalated in between two PF4 monomers in a PF4/H complex." (PMID 34440575, 2021). "Therefore, we measured VEGF, TSP-1, PF4, and PDGF as well as analyzed the epithelial-mesenchymal transition factor TGF-β1 in breast cancer patients and healthy controls." (PMID 25379550, 2014).
hypercoagulability (15 papers, 2018 to 2026). "In other words, an increased PF4 serum level at 10 days post-burn associates with an increased risk of hypercoagulability, reflected by a decreased APTT." (PMID 38792336, 2024). "Due to the formation of this PF4/polyanion complex, thrombocytes are activated and aggregate, leading to thrombophilia with the risk of thromboembolic events and consumption coagulopathy." (PMID 35821156, 2022). "Platelet Factor 4 (PF4), released during platelet activation, is closely associated with platelet dysfunction and hypercoagulability in TIC." (PMID 40300035, 2025). "Although antibodies against PF4–heparin and PF4 bind to distinct epitopes on PF4, both types of antibodies cross-link platelet Fc receptors (FcγRIIA), inducing platelet activation and hypercoagulability." (PMID 40276517, 2025). "Type 2 is a hypercoagulable state resulting from anti-heparin platelet factor 4 (PF4) IgG antibodies." (PMID 37575780, 2023). "Exercise itself induces hypercoagulability, and the combination of rHuEPO and exercise increased E-selectin and PF4 levels more than either intervention alone." (PMID 32537688, 2020). "AGP and PF4 serum levels at 10 days significantly and negatively correlated with APTT values, showing a tendency towards hypercoagulability." (PMID 38792336, 2024). "Thrombophilia evaluation demonstrated factor V Leiden heterozygosity and positive PF4/polyanion ELISA but negative SRA." (PMID 39759125, 2025). "PF4/polyanion ELISA was positive with negative SRA, and extensive thrombophilia evaluation was negative, as was evaluation for other causes for thrombosis (malignancy, inflammatory bowel disease, and rheumatologic)." (PMID 39759125, 2025). "In addition, exercise induced hypercoagulability as observed by significant changes in all measured markers, including TAT, D-Dimer, aPTT, PF4 and Beta-TG." (PMID 32537688, 2020). "We demonstrated that preemptive and non-preemptive patients have a comparable preoperative hypercoagulable state as assessed by PF4, F1+2, and D-dimer levels, Elevation of these markers indicate enhanced in vivo activation of platelets (PF4) and the coagulation system (F1+2, D-dimer)." (PMID 30011293, 2018).
myocardial infarction (15 papers, 2015 to 2024). Gross necrosis of the myocardium, as a result of interruption of the blood supply to the area, as in coronary thrombosis. "In the acute stage of myocardial infarction, plasma fibrinopeptide A (FPA), cross-linked fibrin, platelet factor 4 and fibrinogen degradation products increase." (PMID 36836066, 2023). "PF4, sFRP1 also had a positive relation with history of myocardial infarction (p < 0.05)." (PMID 28947991, 2017). "For positive anti-platelet factor 4 antibodies, VITT with myocardial infarction and azygos vein thrombosis was diagnosed." (PMID 34650896, 2021).
Stroke (15 papers, 2010 to 2024). Sudden impairment of blood flow to a part of the brain due to occlusion or rupture of an artery to the brain. "There is an association between COVID-19-related stroke and platelet factor 4 (PF4) targeted by antibodies produced after the vaccination, which is similar to heparin-induced thrombocytopenia, referred to as VITT." (PMID 38818372, 2024). "PF-4 has previously been associated with stroke risk, infarct size and worse clinical outcomes post-stroke." (PMID 37685924, 2023). "Case series describing VZV related strokes report elevated platelet activation markers, such as PF-4 and β-thromboglobulin levels in some patients." (PMID 33672766, 2021). "Immune response to anti-PF4 antibodies and activation of inflammatory and endothelial cells, as well as inflammatory processes due to the attachment of soluble spike variants to ACE2 on the surface of endothelial cells in blood vessels, contribute to the risk of stroke." (PMID 38818372, 2024). "Although the discussion was mainly focused on the gene SP1 that presented significant expression change in the case of stroke, other genes with minor expression variances may also worth a closer look, including PF4 (LFC: 0.79; p-value< 10–3), CYP4V2(LFC: 0.72; p-value = 0.046)." (PMID 33092540, 2020). "Additionally, plasma levels of PF4 correlated with both plasma H3cit and MPO-DNA levels in our cohort (r = 0.376, P = 0.024, and r = 0.556, P = 0.001, respectively), implying a role for platelet activation in stroke-induced NET formation." (PMID 35358095, 2022).
lung carcinoma (14 papers, 2011 to 2023). "PF4 is a cancer-enhancing endocrine signal, and its overexpression in tumors is associated with reduced OS in patients with lung cancer." (PMID 35962453, 2022). "The platelet factor 4 (PF4) is an endocrine factor with overexpression, associated with low survival of patients with lung cancer." (PMID 33573289, 2021). "In platelets of patients with late-stage (III–IV) lung cancer, we observed a decrease in PF4, CTAPIII, and TSP-1 as compared to the control group, which was similar to a previous study performed in patients with advanced cancer." (PMID 33634328, 2021). "In this study, we used different approaches to capture and analyze CTCs and RNA from patients with malignant lung cancer and subsequently used advanced data mining to augment our findings and to identify an intriguing PF-4-centric network." (PMID 31215484, 2019). "Platelet factor-4 variant chemokine CXCL4L1 inhibits melanoma and lung carcinoma growth and metastasis by preventing angiogenesis." (PMID 27223426, 2017). "In lung cancer patients, Bittner dataset, Oncomine, lower PF4 expression levels were found in stage III compared with stage I." (PMID 27223426, 2017). "The tumor-growth-inhibitory effect of PF4 has also been observed in an animal xenograft model of lung cancer, and in glioblastoma in an orthotopic human glioblastoma model." (PMID 21693026, 2011). "In addition to growth factors, platelet factor 4 (PF4) was found to regulate tumor microenvironment and expedite lung cancer growth." (PMID 34722319, 2021). "PF4-active platelet accumulation in cancer is crucial because platelets can modulate cancer cells and the cancer microenvironment to stimulate lung cancer outgrowth, but this gene might be answerable for development of pituitary prolactinoma." (PMID 33709028, 2021). "However, lung cancer cases also had higher platelet counts (P = 0.08) and PF4 levels (P = 0.02), while residual serum levels of TGF-β1 and VEGF, after accounting for PF4, were unassociated with lung cancer (P = 0.40 and P = 0.15, respectively)." (PMID 25919050, 2015). "Based on our statistical model, lung cancer was associated with PF4, but not with residual levels of TGF-β1 and VEGF, indicating that it was the platelet-related fractions of TGF-β1 and VEGF that were increased." (PMID 25919050, 2015). "The pro-tumorigenic cytokine, TGF-β1, and the chemokine, PF4 (CXCL4), are not only abundant in the α-granules of platelets but are also expressed by many types of human tumor, including lung cancer." (PMID 37569299, 2023). "Intriguingly, platelet factor 4 (PF4), an endocrine factor with overexpression correlating with decreased overall survival of patients with lung cancer, emerged as a central node connected with high confidence to SRGN, SPARC, CLU and CCL5." (PMID 31215484, 2019). "Moreover, PF4, a constituent of the SLB panel, was shown to promote the production of tumor-educated platelets in lung cancer, a platelet subpopulation that stimulates tumor progression and is currently appreciated as a potential analyte in liquid biopsy." (PMID 35008327, 2021).
systemic lupus erythematosus (14 papers, 2016 to 2023). An autoimmune multi-organ disease typically associated with vasculopathy and autoantibody production. "Previous studies have characterized the presence of anti-PF4/heparin Ab in patients with systemic lupus erythematosus (SLE) or anti-phospholipid Ab syndrome." (PMID 27558507, 2016). "Intriguingly, PPBP (CXCL7) and PF4 (CXCL4) belong to the CXC chemokine family, which plays a pivotal role in the development or progression of rheumatoid arthritis (RA), antiphospholipid syndrome, and systemic lupus erythematosus." (PMID 34867780, 2021). "Satoh and colleagues also showed heparin-independent anti-PF4 reactivity in approximately 14% (17/118) of patients with systemic lupus erythematosus; there did not appear to be any correlation between the detection of heparin-dependent and heparin-independent antibodies in these patients." (PMID 37959386, 2023). "A significant proportion of systemic lupus erythematosus and APS patients have auto-anti-PF4 antibodies without a history of heparin treatment." (PMID 35008518, 2021).
Autoimmunity (13 papers, 2017 to 2025). The occurrence of an immune reaction against the organism's own cells or tissues. "Previously, we identified a new mechanism of autoimmunity in HIT in which PF4-antibodies self-clustered PF4 and exposed binding epitopes for other pathogenic PF4/eparin antibodies." (PMID 38540666, 2024). "Exploring the characteristics differentiating anti-PF4(/P) autoantibodies (group-3) from polyanion-dependent antibodies (group-2) bears the potential to better understand mechanisms of antibody-mediated autoimmunity." (PMID 28530237, 2017). "Recently, we identified a new mechanism of autoimmunity mediated by anti-PF4 antibodies (aPF4 Abs)." (PMID 38540666, 2024). "In the second “late” step, between days five and twenty after vaccination, antibodies directed against PF4, resembling those in autoimmune HIT, activate platelets in a PF4- and polyanion-dependent manner." (PMID 35740269, 2022). "In bacterial sepsis, PF4 binds to glycosaminoglycans (GAGs) on the surface of aerobic bacteria, forming an antigenic complex that may induce early generation of anti-GAGs/PF4 IgA-IgG-IgM as a defense mechanism, prompting phagocytosis and contributing to innate immunity and autoimmunity." (PMID 32846949, 2020). "Moreover, a special focus should be placed on investigating anti-PF4-mediated immunothrombosis without prior heparin exposure in patients with autoimmune conditions." (PMID 40573981, 2025). "Antibodies present in patients with autoimmune HIT activate platelets without heparin, and although their role is not yet fully understood, they may promote binding of anti-PF4/H antibodies to PF4 alone." (PMID 32668640, 2020).
fibrosis (13 papers, 2016 to 2025). the formation of excess fibrous connective tissue in an organ or tissue in a reparative or reactive process. "Cardiac fibrosis was undetectable in Pf4-cre.F13a1flox/flox mice, excluding a protective role for FXIII-A in cardiac macrophages, as well as within platelets which are also depleted of FXIII-A." (PMID 31874419, 2020). "Moreover, platelet factor 4 (PF4/CXCL4) was also found to be associated with ultimate AVF failure via a RNA-seq study, while PF4 administration could stimulate expressions of α-SMA and collagen 1 via TGF-β pathways, eventually resulting in venous fibrosis." (PMID 39273465, 2024).
coronary artery disease (12 papers, 2012 to 2026). "Several studies reported that P-selectin and platelet factor 4 (PF4), reflecting platelet activation, had a positive association with PM exposure in healthy young adults and patients with coronary arterial disease." (PMID 35886623, 2022). "In human tissues, FN1, GP1BA, and PF4 were all upregulated in Sudden death from coronary heart disease (SD-CHD) myocardial samples, with FN1 showing the greatest increase." (PMID 41828395, 2026). "Like PF4 and CXCL5, PPBP has received little research attention in the context of ICH, but is considered a potential risk factor for coronary heart disease in patients with hyperlipidemia." (PMID 38271077, 2024). "For the first time, increased levels of CXCL4/PF-4 were found in coronary artery disease, being used as a measure of platelet activation." (PMID 25298751, 2014). "We evaluated the determinants and prognostic value of the platelet-derived chemokines PF-4var, PF-4 and RANTES/CCL5 in patients with stable coronary artery disease (CAD)." (PMID 22384011, 2012).
endothelial dysfunction (12 papers, 2012 to 2025). In vascular diseases, endothelial dysfunction is a systemic pathological state of the endothelium (the inner lining of blood vessels) and can be broadly defined as an imbalance between vasodilating and vasoconstricting substances produced by (or acting on) the endothelium. "The release of P‐selectin and chemokines, including β‐thromboglobulin and platelet factor 4, can promote platelet‐leukocyte interactions and contribute to endothelial dysfunction, potentially impairing vascular integrity and blood flow." (PMID 40434152, 2025). "Proposed mechanisms include vaccine-induced immune thrombotic thrombocytopenia (VITT) via anti-PF4 antibodies, spike protein-mediated endothelial dysfunction, and adjuvant-driven inflammation." (PMID 40733710, 2025). "As PF4 participates in the development of endothelial dysfunction, our secondary objective was to find a link between PF4 and NO in pediatric CKD." (PMID 38137539, 2023). "In diabetic conditions, metabolic stress enhances platelet reactivity and endothelial dysfunction, promoting the release of inflammatory and profibrotic mediators such as thromboxane A2 (TXA2); platelet factor 4 (PF4); regulated on activation, normal T-cell expressed and secreted; and CD40L." (PMID 41255535, 2025). "The presence of angiostatic factors like PF4, collagen type I and IP-10, as recovered from the surgical PEA material from CTEPH patients, may lead to changes in calcium homeostasis and endothelial dysfunction." (PMID 22916307, 2012).